ETS2 (ETS proto-oncogene 2, transcription factor)
Diseases named in the same sentence as ETS2 in open-access papers (continued):
Sharing a sentence is not in itself a finding about the gene and the disease.
tumor (continued). "Aberrant ETS2 expression has been observed in various cancers and its function differs across tumor types." (PMID 41203621, 2025). "In certain malignancies, high ETS2 expression is correlated with increased tumor aggressiveness and poor prognosis." (PMID 41203621, 2025). "Single-cell transcriptomic datasets indicate that ETS2 gene expression is predominantly restricted to the myeloid cell compartment within the GB tumour mass." (PMID 39019900, 2024). "Tumour-associated microglia/macrophages were found to express both ID2 and ETS2 genes, hence validating their expression in myeloid cells in the context of GB tumours." (PMID 39019900, 2024). "ETS2 is a transcription factor that is involved in cell proliferation and migration and has been shown to be closely related to tumor development, angiogenesis, and metastasis." (PMID 38755647, 2024). "Previous studies reported KLF2 promote cell proliferation and ETS1 and ETS2 contribute to angiogenesis, indicating tumor-promoting functions of these tumor-derived clusters." (PMID 37644609, 2023). "Other genes that are associated with poor prognosis and tumor progression, such as ODC1, ERN1, and ETS2, were also downregulated primarily in the samples treated with Se-E2, Se-K2 and Se-C3." (PMID 36839934, 2023). "Then the expression of ETS1 and ETS2 between tumor and normal samples was compared across 33 types of tumors included in the TCGA database." (PMID 36760475, 2023). "The tumor-specific activation of ETS2-SE was further validated by increased enhancer RNA transcription from this region in CRC." (PMID 36609474, 2023). "ETS2, an ETS proto-oncogene 2 transcription factor, is a member of the ETS family of transcription factors that regulates macrophages during inflammation and participates in the regulation of tumor-associated macrophages." (PMID 36582740, 2022). "We also observed significant upregulation of motif-based targets of ETS2 based on ATAC-seq relative to all genes in the TCGA tumor data excluding GBM (P-value < 1e−6, Kolmogorov–Smirnov test) consistent with our analysis." (PMID 36243974, 2022). "ETS2 is a transcription factor and protooncogene involved in development, apoptosis, and regulation of telomerase; ERF acts as tumor suppressor by binding the protooncogene ETS2 promoter." (PMID 34063511, 2021). "The expressions of several ETS family members, such as PEA3, ETS-1, and ETS-2, are upregulated in tumors, playing a role in different aspects of tumorigenesis, including tumor initiation, epithelial-mesenchymal transition, metastasis, and angiogenesis." (PMID 33671331, 2021). "In our study, we found that the methylation level of ETS2 is higher in regrowth patients and that patients with upregulation of ETS2 seem less likely to face with tumour regrowth." (PMID 32015217, 2020). "The effects of ETS2 in cancer are context-dependent, and both oncogenic and tumor suppressive functions have been described." (PMID 31487842, 2019). "Currently, it is largely accepted that ETS2 can act as an oncogene in some cellular backgrounds and as a tumor suppressor in others." (PMID 31487842, 2019). "While we have reported a positive relationship between MTA1 and ETS2 in this study and previously, suggesting a tumor-promoting role for ETS2, the literature evidence remains divided, suggesting both tumor-promoting and tumor-suppressive functions for ETS2." (PMID 31487842, 2019). "The role of ETS2 as a tumor suppressor is also supported by studies showing that PCa with TMPRSS2-ERG fusions generated through the deletion of a region containing ETS2 among other genes, represent a more aggressive and hormone-refractory disease." (PMID 31487842, 2019).
tumor (continued). "In recent years, many studies suggest that ETS2 exhibit both tumor-promoting and tumor-suppressive effects in malignancies." (PMID 28724426, 2017). "The fact that CDK10/CycM promotes ETS2 degradation and inhibits its transcriptional activity would support a tumor suppressor role of the kinase." (PMID 28178678, 2017). "Ets2 was originally identified as a proto-oncogene, but it exhibits both tumor-promoting and -suppressive effect in different types of carcinomas." (PMID 27556183, 2016). "Among those, the ETS2 rs461155A>G was strongly correlated with decreased ETS2 mRNA expression level in both tumor and normal lung tissues." (PMID 26893365, 2016). "It has been reported that ETS2 functions as both oncogene and tumor-suppressor gene in different types of malignancies." (PMID 26893365, 2016). "These GOF activities can arise from novel protein–protein interactions that can either disable other tumor suppressors (e.g., p63 and p73) or enable oncogenes such as ETS2, an ETS family member." (PMID 26925389, 2016). "For example, Ets2 are expressed at much higher levels in neoplasias of the thyroid relative to benign and normal tissues." (PMID 27556183, 2016). "Mice carrying extra copies of ETS2 were protected from tumor development, whereas ETS2 heterozygous mice exhibited higher cancer frequency." (PMID 26925389, 2016). "“Subtracting” one copy of Ets2 from the three copies in Ts1Rhr, ApcMin mice results in significantly increased tumor number relative to Ts1Rhr; Ets2+/- mice with only one functional copy have a dramatic increase in tumor number." (PMID 26752700, 2016). "Previously, it has been shown that Ets2 dosage can impact tumor development in the APCMin mouse model." (PMID 26925389, 2016). "Previous studies have indicated that Ets2 factors are abnormally expressed in both tumor and stromal compartments, which frequently correlates with tumor progression." (PMID 27556183, 2016). "The greater the expression level of the KRT14 and ETS2 genes in the tumor tissues relative to the normal tissues, the greater would be the chance of recurrence." (PMID 25575813, 2015). "Analysis of the expression levels of the genes in tumor tissue indicated significant associations between the KRT14 (p = 0.034) and ETS2 genes (p = 0.0471) and recurrence." (PMID 25575813, 2015). "This role of Ets2 is specific to the stroma since Ets2 is dispensable for tumor progression in malignant epithelial cells." (PMID 23977064, 2013). "First, the genetic studies demonstrate that Ets2 regulates an oncogenic gene expression program in tumor stromal fibroblasts that promotes tumor growth." (PMID 23977064, 2013). "The activation of Ets2 stromal fibroblast-specific expression programs represents one mechanism by which the tumor co-opts the microenvironment to serve in its progression to malignancy." (PMID 23977064, 2013). "Defining and targeting the pathway hubs controlled by Ets2 provides an alternative strategy that should be more effective at altering multiple cell-cell and cell-matrix interactions required for tumor angiogenesis." (PMID 23977064, 2013). "Analysis of gene expression in fibroblasts revealed a tumor- and Ets2-dependent gene signature that was enriched in genes important for ECM remodeling, cell migration, and angiogenesis in both PyMT and ErbB2 driven-tumors." (PMID 23977064, 2013). "A second significant finding presented here is that the consequence of inactivating this Ets2-driven stromal program is tumor specific, sparing normal development of the mammary gland." (PMID 23977064, 2013). "In conclusion, we have identified Ets2 as a fibroblast-specific effector of tumor growth through a mechanism that involves increased tumor angiogenesis." (PMID 23977064, 2013). "Our results indicate that the changes in tumor angiogenesis observed in vivo are likely regulated by the cumulative action of many Ets2 target genes acting in concert." (PMID 23977064, 2013).
tumor (continued). "The data reveals a key function for Ets2 in tumor fibroblasts in signaling to endothelial cells to promote tumor angiogenesis." (PMID 23977064, 2013). "This approach revealed that fibroblast Ets2 promotes tumor growth and progression, whereas its function in epithelial cells is dispensable for tumor progression." (PMID 23977064, 2013). "There were significantly positive correlations between SRC-1, SRC-2/TIF-2 and HER-2, and between SRC-3/AIB1, HER-4 and Ets-2 mRNA levels in tumor tissue." (PMID 22703232, 2012). "Positive correlations between OPN intensity and that of PEA3 (r=0.600; P<0.01), Ets1 (r=0.552; P<0.01), Ets2 (r=0.521; P<0.01) were observed in primary tumours." (PMID 21343932, 2011). "In the majority of matched pairs, OPN expression was decreased or unchanged in the liver metastasis compared with the primary tumour, whereas Ets1, Ets2, PEA3, Tcf4 and β-catenin were predominantly increased." (PMID 21343932, 2011). "We studied the expression of target genes encoding ICAM-1, PAI-1, MCP-1, and p16 to determine the potential roles of ETS-1 and ETS-2 in the development of this tumor." (PMID 18958307, 2008). "The study identified tumor initiating cells which express ETS2, SLC12A2 and LEFTY1." (PMID 41282138, 2025). "In addition, IHC staining was performed on xenograft tumor tissues to assess the expression of ETS2 and ZMYND11." (PMID 40938895, 2025). "Additionally, IHC analysis demonstrated that ETS2 expression was markedly higher in normal tissue relative to THCA tumor tissue." (PMID 40938895, 2025). "Cellular senescence is crucial in tumor progression, with ETS2 emerging as a key regulator." (PMID 40938895, 2025). "Despite it never being found mutated in tumor-predisposing conditions, ETS2 appears to act more precisely as a tumor repressor rather than a suppressor gene." (PMID 38255007, 2024). "Interestingly, this is in contrast to our study of ETS2 inhibition in NRGMS, where an important function of ETS2 has been shown in numerous studies to be cell cycle protein D1 promoter regulation, thereby shortening the cell cycle and promoting tumor growth." (PMID 38285218, 2024). "Thus, these analyses advocate for the involvement of the transcription factor ETS2 in the regulation of the acquisition of a microglial tumour-supportive phenotype." (PMID 39019900, 2024). "Depending on the biological event, the ETS2 gene functions in tumor suppression or oncogenesis." (PMID 37107558, 2023). "ETS1 and ETS2 are also involved in tumor suppression under some situations." (PMID 36760475, 2023). "CELF1 can foster the migration and invasion of tumor cells by targeting ETS2 and other genes." (PMID 35126520, 2022). "Moreover, expression of ETS-family transcription factors is essential for EC differentiation, with ETS1 and ETS2 affecting tumor angiogenesis and metastasis in the tumor microenvironment, especially in ECs46,47." (PMID 36064747, 2022). "In COAD, ETS2 can induce oxaliplatin resistance and promote the malignant behavior of tumor cells." (PMID 34603375, 2021). "On the other hand, some studies have demonstrated that (i) the ectopic expression of ETS2 decreased the proliferation and invasion of PCa cell lines and (ii) a reduced expression of ETS2 was associated with biochemical recurrence and lethal disease, suggesting a tumor-suppressive role for ETS2." (PMID 31487842, 2019). "We found a significantly higher level of ETS2 in tumor samples compared to normal prostate tissues." (PMID 31487842, 2019).
tumor (continued). "This is consistent with previous studies indicating ETS-2 is tumor suppressive." (PMID 29915163, 2018). "Because ETS2 dosage can repress or promote tumor growth, elevated levels of ETS2 in STAR patients might protect them from the occurrence of certain types of cancers, and might increase their chances of developing others." (PMID 28178678, 2017). "Moreover, in vivo, Xenograft mouse model studies showed Ets2 knockdown inhibits tumor formation and metastasis significantly." (PMID 27556183, 2016). "The tumor-promoting/−suppressive effects of Ets2 might depend on the protein expression with potentially important functions in the tumor microenvironment, including growth factors, adhesion molecules, extracellular proteases and anti-apoptotic genes." (PMID 27556183, 2016). "Moreover, E-cadherin was also increased in Ets2-knockdown tumor tissues compared to tumor-bearing control tissues (P < 0.001)." (PMID 27556183, 2016). "Silencing Ets2 expression inhibited tumor growth and induced a decrease in tumor weight and volume." (PMID 27556183, 2016). "Moreover, increased mRNA levels were found for the transcription factors Jun, ETS2, and NFκβ1, which e.g. regulate the expression of tumor angiogenesis genes." (PMID 24528603, 2014). "The FOS/JUN/ETS2 plays important roles in tumor invasion and metastasis." (PMID 25137136, 2014). "In either scenario, cell context is critical in determining whether Ets2 promotes tumor progression." (PMID 23977064, 2013). "Among the upregulated genes, we identified several oncogenes (Ets2, Fyn, Fos, Rab30 and Src), various tumor markers (Cyp1b1, Gpa33, Cd47, Fam129a, st7l, chka, Lgalsbp, Antxr1 and Ly6a) and other genes related to tumor promotion (Cxcl10, Trim25, Grn, Foxc2, Bmp7 and Irs1)." (PMID 23936067, 2013). "Thus, inhibition of Ets2 expression by either its genetic deletion or miR-320 overexpression attenuated the promotion of tumour growth by these fibroblasts." (PMID 24216702, 2013). "In addition to PEA3/E1AF, other ETS family proteins like ETS-1 and ETS-2 have also been reported to be involved in tumor metastasis." (PMID 24260201, 2013). "As a downstream effector of the Ras/Raf/MAPK pathway, Ets2 regulates the expression of a number of genes with potentially important functions in the tumor microenvironment, including growth factors, adhesion molecules, extracellular proteases and anti-apoptotic genes." (PMID 23977064, 2013). "Our observations could also be explained by epigenetic changes in tumor cells having differential effects on the regulation of genes encoding transcription factors and/or cotranscriptional regulators of ETS-1 and ETS-2." (PMID 18958307, 2008). "ETS2 may act to switch oncogenic role to tumor suppressive role." (PMID 36760475, 2023). "The anti-tumour effects of Rec8 are caused by downregulation of cell growth-related genes (G6PD, SLC2A1, NOL3, MCM2, SNAI1, and SNAI2) and also by upregulation of both apoptosis or migration inhibitors (Gadd45G and LDHA) and tumour inhibitors (PinX1, IGFBP3, and ETS2)." (PMID 36139540, 2022). "Moreover, specific molecular mechanisms may allow ETS2 to switch between oncogenic and tumor suppressive functions in a cell-type and genetic context-specific manner." (PMID 31487842, 2019). "Furthermore, Tunel assay showed that apoptotic rate was 17.4% in Ets2 depleted tumor tissue." (PMID 27556183, 2016). "Our data also suggest that CSK low CRPCs might respond to inhibition of pathways and cellular processes set into motion by loss of ETS2 and ZFHX3 function, two tumor suppressors specifically involved in the transition to CRPC, although regimens to do so remain to be discovered." (PMID 26091350, 2015).
tumor (continued). "Although the exact genes regulated by Ets2 in mammary fibroblasts vary depending on the oncogenic signals coming from the tumor cell, there is a significant overlap of target genes and the overall outcome of increased tumor growth and tumor angiogenesis remain consistent with both oncogenes tested." (PMID 23977064, 2013). "The results of this investigation underscore the significant regulatory roles of ETS2 and ZMYND11 in THCA and their impact on tumor progression." (PMID 40938895, 2025). "Specifically, NAT10 enhances the stability of ETS2 and KRT8 mRNA via ac4C modification, thereby promoting tumor malignancy and immunosuppression." (PMID 41203621, 2025). "In conclusion, this study established NAT10 as a central regulator of PC progression and immune evasion through the ac4C-dependent stabilization of ETS2 and KRT8 mRNA, thereby promoting tumor immunosuppression and malignancy." (PMID 41203621, 2025). "The expressions of SHISA5, SERPINE1, and IL1A were markedly high in tumor tissues, whereas those of TP53AIP1, ETS2, and FOS were high in the normal tissues." (PMID 38435998, 2024). "CD44, ETS2, RHOH, and TRIB1 also affect the proliferation and invasion ability of tumor cells by regulating the expression of downstream genes." (PMID 39684426, 2024). "Along with the TFs NF‐κB, C/EBPβ, ETS2, and HIF1A that have been well‐documented as tumor promoters, JUN and its 17 downstream target genes were also categorized in this highly active module." (PMID 34459128, 2021). "The progression-free analysis found that FAM90A1, ETS2, STAT6, MYT1L, ING2 and KCNK1 are related to tumour regrowth." (PMID 32015217, 2020). "For example, ETS2 has been found to be an oncogene in patients with AML, but it also has tumor-suppressive effects in non-small cell lung cancer." (PMID 28724426, 2017). "Phosphorylation of Ets sub-family members, Ets-1 and Ets-2, by MAPK-dependent pathways leads to persistent expression of tumour-related target genes including proteases such as uPA and MMPs." (PMID 17060941, 2006). "CXCL1 was positively correlated with ETS2, and PLEC was negatively correlated with TUBB2, suggesting that these genes may affect tumor development through synergistic effects." (PMID 41523911, 2026). "In vivo, a xenograft model was established using Cal-62 cells with or without ETS2 overexpression to assess tumor growth and protein expression." (PMID 40938895, 2025). "Interestingly, we detected tcGT events with a known tumor suppressor gene RNF43 and two oncogenes ETS2 and SLCO1B3 supporting the extensive contribution of TEs during tumorigenesis." (PMID 38272908, 2024). "While Ets2 supported general inflammatory responses in tissue macrophages, Ets2 in mammary TAM did not elicit antitumoral responses but promoted tumour angiogenesis." (PMID 39720957, 2024). "Own in silico analyses revealed substantial ETS1 and ETS2 expression in non-neoplastic brain and tumor tissue." (PMID 37697350, 2023). "Ets2 is a downstream target for both the Ras/Raf/MAP kinase and phosphatidylinositol 3-kinase/Akt pathways, regulating the expression of a number of genes with potentially important functions in the tumor microenvironment." (PMID 27556183, 2016). "Of additional note, even though ETS2 was detected in the stromal cells, ETS2 protein was selectively absent in the Ets2-shRNA-transduced tumor masses." (PMID 26590320, 2015). "A recent study indicated that downregulation of miR-320 and upregulation of one of its direct targets, ETS2, were critical events in phosphatase and tensin homolog deleted on chromosome ten (PTEN)-deleted stromal fibroblasts responsible for promoting tumor angiogenesis and tumor cell invasion." (PMID 23418466, 2013).